GPNMB (glycoprotein nmb)
Diseases named in the same sentence as GPNMB in open-access papers (continued):
Sharing a sentence is not in itself a finding about the gene and the disease.
lung carcinoma (6 papers, 2015 to 2025). "Concerning lung cancer, it was reported that GPNMB/OA overexpression was associated with decreased overall survival among small-cell lung cancer (SCLC) patients." (PMID 26883195, 2016). "Mounting evidence establishes GPNMB as a critical player in lung cancer progression through dual oncogenic mechanisms." (PMID 41180454, 2025). "The current work is based on the premise that potential consideration of GPNMB/OA as a therapeutic target for lung cancer will require a deeper understanding of potential impact of GPNMB/OA expression and shedding of its ECD protein." (PMID 26883195, 2016). "Taken together, our results accentuate the relevance of GPNMB/OA ECD protein shedding to progression of lung cancer." (PMID 26883195, 2016). "Additional mechanistic studies are warranted to elucidate the effects of GPNMB/OA ECD protein on lung cancer growth as well as the impact of possible interaction of GPNMB/OA ECD protein with RGD-binding integrins on lung cancer progression." (PMID 26883195, 2016). "The work reported herein underscores the importance of suppressing GPNMB/OA expression and/or negating GPNMB/OA ECD protein shedding as potential therapeutic strategies in lung cancer." (PMID 26883195, 2016). "Additional mechanistic studies are warranted to fully elucidate the role of GPNMB/OA ECD protein in lung cancer progression." (PMID 26883195, 2016). "Further studies showed that silencing GPNMB/OA expression in lung cancer cells markedly diminished the extent of GPNMB/OA ECD shedding and invasive behavior (the number of migrated cells)." (PMID 26883195, 2016). "The trend connotes that lung cancer cells with high GPNMB/OA mRNA expression level should be expected to secrete more GPNMB/OA ECD protein." (PMID 26883195, 2016). "Notably, the expression of GPNMB was found to be significantly higher in LN compared to primary lung cancer." (PMID 38706915, 2024). "Moreover, other studies have indicated that GPNMB fosters invasion, migration, and metastasis of lung cancer cells 17, albeit these findings were predominantly based on NSCLC." (PMID 38706915, 2024). "The findings from our work thus suggest that potential application of GPNMB/OA as a therapeutic target for lung cancer should incorporate strategies that will inhibit the mechanism by which GPNMB/OA ECD protein is shed or negate the effects of the GPNMB/OA ECD protein in tumor tissues." (PMID 26883195, 2016). "Thus, it is likely that the function of GPNMB/OA in promoting invasive and aggressive behavior in lung cancer cells was achieved through shedding of its ECD protein." (PMID 26883195, 2016). "Thus, strategies that suppress GPNMB/OA expression on lung cancer cells as well as negate shedding of GPNMB/OA ECD protein are worthy of consideration in lung cancer therapeutics." (PMID 26883195, 2016). "In this regard, we hypothesized that overexpression of GPNMB/OA on lung cancer cells will directly result in increased shedding of GPNMB/OA ECD protein that will facilitate lung cancer growth." (PMID 26883195, 2016). "Thus, in this work that the pro-tumor and pro-metastatic function of GPNMB/OA in lung cancer is most likely propagated through shedding of the ECD protein into tumor tissues which could play a major role in creating favorable environment that supports tumor growth." (PMID 26883195, 2016). "In this study, we examined the expression and function of osteoactivin (OA)/(glycoprotein non-metastatic melanoma B; (GPNMB) in lung cancer progression." (PMID 26883195, 2016). "Thus, in this work we characterized GPNMB/OA expression and extent of shedding of its ECD protein while evaluating the impact on lung cancer progression using three non-small cell lung cancer (NSCLC) cell lines: A549, SK-MES-1 and calu-6." (PMID 26883195, 2016). "Some studies suggest that disorders of glycoprotein metabolism may be useful as prognostic indicators in patients with lung cancer, such Glycoprotein nonmetastatic melanoma B (GPNMB) and P-glycoprotein." (PMID 33291317, 2020).
multiple sclerosis (6 papers, 2018 to 2026). A progressive autoimmune disorder affecting the central nervous system resulting in demyelination. "Researchers have associated foamy microglia enriched with GPNMB (a gene product of the Gpnmb human ortholog) with poorer outcomes in patients with multiple sclerosis, implicating GPNMB as a potential marker for lesion-exacerbating foamy microglia in multiple sclerosis." (PMID 41196656, 2025).
amyloid (5 papers, 2021 to 2024). "The same study also investigated the role of GPNMB on amyloid-associated pathology in the 5xFAD mouse model." (PMID 38037070, 2023). "Moreover, the findings of our study showed higher concentrations of GPNMB in AD Aβ(+) patients in comparison to the Aβ(−) group, indicating a connection to amyloid pathology, which may be a result of the neuroprotective activity of GPNMB in the brain areas affected by amyloid plaques." (PMID 37510803, 2023).
diabetes (5 papers, 2021 to 2026). "Higher serum levels of GPNMB are linked to type 2 diabetes mellitus (T2DM) and metabolic dysfunction-associated steatotic liver disease (MASLD)." (PMID 41800647, 2026). "Based on the results of previous research, it was quite possible that the increased circulating levels of GPNMB caused abnormal phosphorylation of AKT via binding to CD44 and then stimulated anomalous activation of AKT/PI3K signaling to promote lipogenesis and provoke diabetes." (PMID 36875463, 2023). "The correlation between OPG and GPNMB was positive and significant irrespective of ethnicity and diabetes status." (PMID 38790981, 2024). "People with diabetes had significantly higher median OPG, RANKL, and GPNMB concentrations than those without T2D." (PMID 38790981, 2024).
malignant glioma (5 papers, 2012 to 2023). A grade III or grade IV glioma arising from the central nervous system. "The high upregulation of GPNMB expression in TAMs was associated with the poor prognosis of malignant glioma." (PMID 37194413, 2023). "Survival analysis revealed that patients with relatively high GPNMB transcript levels, >3-fold over normal brain, as well as positive immunohistochemistry, had a significantly higher risk of death, making GPNMB an ideal target for the treatment of malignant glioma." (PMID 22400035, 2012). "Furthermore, we identified GAMs as the predominant source for the pro-tumorigenic proteins GPNMB and SPP1 in murine and human malignant glioma – highlighting the importance of macrophages and microglia as therapeutic targets in anti-tumor treatment regimens." (PMID 25658639, 2015).
metastatic melanoma (5 papers, 2023 to 2025). A melanoma that has spread from its primary site to another anatomic site. "In clinical study, CD14+HLA−DRno/low cells from metastatic melanoma patients showed increased GPNMB expression." (PMID 38140790, 2023). "However, dasatinib treatment can also increase the expression of a different biomarker called glycoprotein non-metastatic melanoma B (gpNMB), in which high levels of gpNMB on the surface of TNBC cells is associated with lower overall survival of patients." (PMID 36900378, 2023). "Glycoprotein non-metastatic melanoma protein B (GPNMB) was first identified in a cell line of non-metastatic melanoma and named after this." (PMID 37919457, 2023). "Glycoprotein non-metastatic melanoma protein B (GPNMB) got its name from the first discovery in a cell line of non-metastatic melanoma." (PMID 37919457, 2023). "Our data show that the expression of GPNMB on the cell surface marks the quiescent phenotype and exhibits invasive and therapy-resistant features together with a significant negative correlation with KI67 levels in metastatic melanoma patients." (PMID 40528051, 2025).
Parkinson (5 papers, 2018 to 2025). "And these Parkinson’s patients had more severe symptoms, indicating that GPNMB is a novel PD risk and biomarker, and may serve as a potential target for PD treatment." (PMID 37483347, 2023).
pulmonary fibrosis (5 papers, 2023 to 2026). Chronic progressive interstitial lung disorder characterized by the replacement of the lung tissue by connective tissue, leading to progressive dyspnea, respiratory failure, or right heart failure. "This study aims to explore the pathological mechanisms of GPNMB underlying pulmonary fibrosis progression to reveal new therapeutic targets." (PMID 37468937, 2023). "In this study, we attempted to reveal the full mechanism of GPNMB involvement in the pulmonary fibrosis process using multiple modalities." (PMID 37468937, 2023). "Administration of gpNMB-neutralizing antibodies reduced the severity of pulmonary fibrosis." (PMID 41152894, 2025). "CD9+TREM2+ macrophages expressing GPNMB, SPP1, FABP5, and CD63 were reported in murine and human pulmonary fibrosis, enriched at the edges of scars." (PMID 37756565, 2023). "Macrophage-derived glycoprotein nonmetastatic melanoma protein B (GPNMB) is trapped by fibrotic extracellular matrix in a pulmonary fibrosis model and may activate resident normal fibroblasts, promoting fibrosis." (PMID 36732560, 2023). "However, our study could not exclude the fact that GPNMB from other cells may also be involved in the process of pulmonary fibrosis induced by silica." (PMID 36732560, 2023). "Moreover, glycoprotein nonmetastatic melanoma protein B (GPNMB) was identified as one of the most highly upregulated proteins that might be related to the pulmonary fibrosis process in silica-treated mice according to protein interaction network analysis." (PMID 36732560, 2023).
autoimmune disease (4 papers, 2015 to 2024). A disorder resulting from loss of function or tissue destruction of an organ or multiple organs, arising from humoral or cellular immune responses of the individual to their own tissue constituents. "In autoimmune diseases, GPNMB has anti-inflammatory properties, primarily exhibited in macrophages, where it suppresses the production of pro-inflammatory cytokines such as IL-6 and IL-12p40." (PMID 39263169, 2024). "Furthermore, the interaction between GPNMB on antigen-presenting cells and syndecan-4 on T cells inhibits T-cell activation, which is relevant in T cell-driven autoimmune diseases." (PMID 39263169, 2024). "GPNMB is involved in metabolism, inflammation, cell differentiation, migration, and neuroprotection and has been reported to be related to inflammation, neurodegenerative diseases, and autoimmune diseases." (PMID 37786733, 2022). "For both aspects, specific manipulation of GPNMB expression could be of clinical use for the development of novel treatment approaches for malignant and autoimmune disease." (PMID 25889792, 2015). "GPNMB is involved in immune system function and is highly expressed in a variety of innate immunity cells, which may play an important role in the pathogenesis of autoimmune diseases." (PMID 35784282, 2022).
dementia (4 papers, 2021 to 2024). Loss of intellectual abilities interfering with an individual's social and occupational functions. "The area under the receiver operating characteristics (ROC) curve (AUC) was 0.59 for CSF GPNMB alone (95% CI 0.49, 0.69), indicating poor ability to discriminate between AD patients and dementia of other causes." (PMID 33947460, 2021). "There were significant positive interaction effects of GPNMB gene expression on Aβ-tau in the non-dementia group in the HIP and TCx brain regions (β = 0.089, p = 0.02 and β = 0.026, p < 0.001 in HIP and TCx, respectively)." (PMID 39554095, 2024). "Based on linear regression with histopathological and gene expression data, GFAP and IBA1 levels and GPNMB gene expression positively contributed to the interaction of tau with Aβ in non-dementia cases, replicating the results of the network analysis." (PMID 39554095, 2024). "According to these findings, GPNMB and YKL-40 may help distinguish early stages of dementia (MCI) from cognitively normal subjects, as well as AD dementia from controls without cognitive impairments." (PMID 37510803, 2023).
head and neck squamous cell carcinoma (4 papers, 2022 to 2025). A squamous cell carcinoma that arises from any of the following anatomic sites: lip and oral cavity, nasal cavity, paranasal sinuses, pharynx, larynx, and salivary glands. "For breast and Head and Neck Squamous Cell carcinoma it has been reported that a subgroup of cancer stem cells express GPNMB and utilize it to persist." (PMID 38566120, 2024). "GPNMB-positive cells exhibit cancer stem cell characteristics in head and neck squamous cell carcinoma (HNSCC), the GPNMB positivity rate is expected to be approximately 15%." (PMID 41180454, 2025).
Insulin resistance (4 papers, 2023 to 2024). Increased resistance towards insulin, that is, diminished effectiveness of insulin in reducing blood glucose levels. "GPNMB-ECD overexpressing mice displayed severe insulin resistance, in which treatment with GPNMB-neutralizing antibodies significantly improved metabolic parameters and insulin sensitization." (PMID 38789534, 2024).
iris disease (4 papers, 2008 to 2016). "To genetically test whether the GPNMB genotype of BM derived lineages influences the D2 iris disease, we took advantage of the DBA/2J substrain, D2-Gpnmb+ that has a wild-type Gpnmb allele but no other known differences to modern D2 mice." (PMID 18402690, 2008). "DBA/2J mice with wild type GPNMB develop very mild iris disease with no retinal ganglion cell loss." (PMID 18822132, 2008).
ischemic stroke (4 papers, 2017 to 2025). A stroke disorder caused by obstruction of blood flow to the brain, due to thrombotic (local blood clot formation) or embolic (due to a blood clot or other material traveling from another site) event. "Results from prior studies show that IL21R, BMF, and GPNMB correspond to mediators of injury following ischemic stroke." (PMID 28097054, 2017). "The GPNMB, although not previously studied in SAH, demonstrates significant upregulation in ischemic stroke." (PMID 38702954, 2024).
lung disease (4 papers, 2024 to 2025). "Overall, plasma gpNMB concentrations show potential for detecting fibrotic liver and pulmonary disease and MGUS." (PMID 41152894, 2025). "The mechanism of GPNMB in lung diseases is a complex network involving multiple aspects and is of great significance for disease research." (PMID 41180454, 2025). "In the research related to lung diseases, GPNMB mainly serves as a marker of the recruited macrophage subset." (PMID 41180454, 2025). "Compared with healthy subjects, median gpNMB concentrations in the GAUCHERITE Cohort were increased 7, 7, 15 and 17-fold in patients with splenectomy, pulmonary disease, monoclonal gammopathy and liver disease, respectively." (PMID 41152894, 2025). "Patients with pulmonary disease (n = 29) had higher plasma gpNMB concentrations compared with those without pulmonary involvement (n = 163) (p = 0.038)." (PMID 41152894, 2025). "Analogous GPNMB-expressing macrophages were identified in datasets from both fibrotic and nonfibrotic lung disease in humans." (PMID 39509324, 2024). "Relatedly, GPNMB expression later in the disease process, primarily in M2-alveolar macrophages, could also contribute to basal ESC reprogramming toward lung disease." (PMID 39052353, 2024).
ovarian carcinoma (4 papers, 2019 to 2025). A malignant neoplasm originating from the surface ovarian epithelium. "In the ovarian cancer cells where miR-532-3p was overexpressed, the levels of GPNMB were decreased both at the RNA and protein levels." (PMID 41180454, 2025). "When studying the relationship between the expression of GPNMB and the clinical characteristics of epithelial ovarian cancer, it was discovered that its expression level is closely related to the staging of ovarian cancer." (PMID 41180454, 2025). "Through immunohistochemical analysis of tissue samples and real-time quantitative PCR for biopsy of living tissues, it has been found that compared with normal tissues, GPNMB is highly expressed in various types of epithelial ovarian cancer, such as serous carcinoma and endometrioid carcinoma." (PMID 41180454, 2025). "Furthermore, comparison of the CACiv signature to a published gene signature of tumor-derived endothelium (ovarian carcinoma) yielded only one tumoral vascular marker, GPNMB, which was upregulated in both profiles." (PMID 31191690, 2019). "This suggests that GPNMB may be a target for the diagnosis and treatment of ovarian cancer." (PMID 41180454, 2025).
renal tumors (4 papers, 2010 to 2026). "We examined GPNMB expression as a readout of TFE3 transcriptional activity in the renal tumors from BHD patients." (PMID 21209915, 2010). "GPNMB expression was also high in the UOK146 cell line that was established from a sporadic kidney tumor harboring a chromosomal translocation, t(X;1)(p11.2;q21), which expressed a high level of the resulting gene fusion product, PRCC-TFE3." (PMID 21209915, 2010). "However, since the survey was conducted, an emerging marker, GPNMB, appears to show promise for recognizing renal neoplasms with MITF family translocations and TSC/MTOR pathway alterations, which was not assessed in this study." (PMID 39287823, 2024). "Immunohistochemical staining further confirmed that GPNMB expression was exclusively located in the tumor portion but not in the normal kidney portion of sections from BHD patients and Flcn+/− heterozygote mouse renal tumors." (PMID 21209915, 2010). "In accordance with the TFE3 staining pattern, GPNMB expression was restricted to renal tumor cells and was absent from embedded normal renal tubules (bottom left)." (PMID 21209915, 2010). "GPNMB expression was highly dependent on FLCN inactivation not only in cultured cells but also in the kidneys and renal tumors of the human patient and in vivo mouse models." (PMID 21209915, 2010). "Specifically, high levels of GPNMB expression were found in all of the renal tumors (N = 11) from BHD patients, but none of the normal kidney tissues (N = 5), suggesting that GPNMB might serve as a biomarker for BHD syndrome and a therapeutic target for treatment of BHD renal tumors." (PMID 21209915, 2010).
steatosis (4 papers, 2015 to 2025). Increased lipid within the cytoplasm of cells. "Additionally, serum GPNMB protein level were found to be increased in type 2 diabetics compared to healthy controls and further increased in people with simple steatosis and with biopsy proven NASH." (PMID 29799853, 2018). "For instance, serum concentrations of GPNMB were reported to be higher in people with NASH (no-alcoholic steatohepatitis) than in individuals with simple steatosis." (PMID 38790981, 2024).
type 1 Gaucher disease (4 papers, 2016 to 2025). "To explore its potential significance in GD we measured plasma gpNMB in patients with Gaucher Disease type 1 (GD1), Gaucher Disease Type 3 (GD3), GD1-PD, PD and GBA heterozygous PD and in different clinicopathological subtypes." (PMID 41152894, 2025). "In a genetically modified mice model of type 1 Gaucher Disease, GPNMB levels were also increased, and after treatment, GPNMB levels returned to normal." (PMID 34054862, 2021).